TIMP3 (TIMP metallopeptidase inhibitor 3)
Diseases named in the same sentence as TIMP3 in open-access papers (continued):
Sharing a sentence is not in itself a finding about the gene and the disease.
bladder cancer (9 papers, 2010 to 2026). "Both RASSF1A and TIMP3 are tumor suppressor genes, which have been found hypermethylated in bladder cancer." (PMID 23527093, 2013). "TIMP3 methylation was also previously found associated with better survival in NSCLC, and bladder cancer." (PMID 20849603, 2010). "Notably, overexpression of TIMP3 reversed the alterations in bladder cancer cell behavior induced by HIF-1α knockdown." (PMID 41680285, 2026). "Furthermore, the metalloprotease inhibitor 3 encoding gene (TIMP3) correlates with metastasis and poor prognosis in gastric, colorectal, breast, brain, HNSCC, and bladder carcinoma." (PMID 32010630, 2019). "Further studies are warranted to elucidate the transcriptional regulation of TIMP3 by HIF-1α and to validate its role in vivo, which may contribute to the advancement of targeted therapeutic strategies for bladder cancer." (PMID 41680285, 2026). "Among the main repressed genes in bladder cancer, there are fatty acid binding protein 4 (FABP4) and fibroblast growth factor binding protein 1 (HBP17), RGS4, tissue inhibitor of metalloproteinase 3 (TIMP3), WNT5b, URB, and collagen type VIII, alpha 1 (COL8A1)." (PMID 34835969, 2021).
lung adenocarcinoma (9 papers, 2015 to 2025). A carcinoma that arises from the lung and is characterized by the presence of malignant glandular epithelial cells. "In this study, significant downregulation of TIMP3 was detected in several cancer types, such as lung adenocarcinoma (LUAD), kidney chromophobe (KICH), lung squamous cell carcinoma (LUSC), and uterine carcinosarcoma (UCS) tissues, in addition to CRC." (PMID 41009435, 2025). "It is also observed that IL-6 expression increased TIMP-3 methylation in lung adenocarcinoma and also increased cyp enzymes methylation in colon cancer." (PMID 29467412, 2018). "First, we analyzed the expression of TIMPs in lung adenocarcinoma in the TCGA database and found that only TIMP2 and TIMP3 expression were significantly down-regulated in tumors compared to normal controls." (PMID 27058897, 2016).
lymph node metastasis (9 papers, 2014 to 2024). "Within male patients harboring a mutant EGFR, TIMP-3 rs9862 T (CT+TT) allele carriers were at higher risk of developing an advanced stage (p = 0.025) and lymph node metastasis (p = 0.043)." (PMID 33126605, 2020). "In addition, among male subjects having mutant EGFR, patients carrying allele T in TIMP-3 rs9862 exhibited a higher risk of displaying an advanced stage and positive lymph node metastasis." (PMID 35813301, 2022). "In the same study, the authors found that TIMP-3 expression was correlated to the depth of tumoral invasion, lymph node metastasis, and infiltrative growth pattern and stage of the disease; thus, the prognosis for EC patients who present a reduction in expression of TIMP-3 is less favorable." (PMID 24669030, 2014). "Additionally, the statistical results revealed that positive TIMP-3 expression was negatively correlated with portal vein invasion (p = 0.036) and lymph node metastasis (p = 0.030)." (PMID 25171061, 2014). "Most mice developed neck lymph node metastasis within 35 days after cancer cell injection; we further determined the frequency of neck lymph node metastasis and the volume of lymph nodes excised from the TW2.6/pcDNA3 and TW2.6/TIMP3 groups." (PMID 31624299, 2019). "It is of note that positive TIMP-3 expression was more prevalent in patients with a lack of portal vein invasion and no lymph node metastasis." (PMID 25171061, 2014).
oral cancer (9 papers, 2017 to 2023). "TIMP3 plasma levels were significantly lower in oral cancer and were associated with tumor stage and size." (PMID 33918195, 2021). "Male oral cancer patients in Taiwan who carried the “T” allele of the rs9862 variant of the TIMP3 gene had increased plasma levels of TIMP3 molecule." (PMID 28081267, 2017). "Loss of TIMP-3 resulted in worse outcomes for oral cancer patients and increased metastasis." (PMID 36555545, 2022). "In previous studies, both oral cancer and UCC are associated with epithelial agent 16-20, plus the TIMP-3 can alter the activity of the matrix metalloproteinases which is related to the UCC development." (PMID 36860920, 2023). "Epigenomic hypermethylation of the TIMP-3 promoter region was observed to reduce transcriptional activity in lung, kidney, brain, and oral cancers." (PMID 33126605, 2020). "In conclusion, these results suggest that the suppression of TIMP3 by DNA methylation contributes to oral cancer metastasis." (PMID 31624299, 2019). "In the present data, knockdown of DNMT1 or DNMT3B restored the expression of TIMP3 in the oral cancer cell lines." (PMID 31624299, 2019). "TIMP3 restoration in oral cancer cell lines reduced wound healing, migration, and invasion abilities." (PMID 31624299, 2019). "Nevertheless, we demonstrated that TIMP3 plays a crucial role in regulating migration and invasion processes in oral cancer." (PMID 31624299, 2019). "In conclusion, our findings suggested that the suppression of TIMP3 by DNA methylation contributes to oral cancer metastasis." (PMID 31624299, 2019). "We observed that TIMP3 changed the cell morphology from fibroblastic- to epithelial-like islands and increased the cell adhesion ability in oral cancer." (PMID 31624299, 2019). "Functional analyses revealed that TIMP3 overexpression reduced migration and invasion abilities in oral cancer cells and inhibited lymph node metastasis in vivo." (PMID 31624299, 2019). "Overexpression of TIMP-3 was shown to suppress EMT-induced metastasis in oral cancer." (PMID 33126605, 2020). "Therefore, in the present study, we investigated the relationship between TIMP3 and oral cancer by analyzing TIMP3 expression in oral cancer cell lines and oral tissues obtained from patients with oral cancer." (PMID 31624299, 2019). "In summary, we identified TIMP3 as a clinical marker for predicting oral cancer." (PMID 31624299, 2019). "In this study, TIMP3 suppression enhanced the expression of Snail and Twist in oral cancer cells." (PMID 31624299, 2019). "Although studies have identified TIMP3 as a tumor suppressor gene in many cancer types, few reports still exist on whether the abnormal expression and promoter methylation of TIMP3 facilitates oral cancer metastasis." (PMID 31624299, 2019). "Moreover, in vitro data demonstrated that TIMP3 mRNA and protein levels were downregulated in oral cancer cell lines compared with normal oral cell lines (HOK and SG)." (PMID 31624299, 2019). "After treatment with 5-aza, the TIMP3 mRNA level was elevated in all oral cancer cell lines." (PMID 31624299, 2019). "Finally, we determined the function of TIMP3 in oral cancer by transfecting a TIMP3 overexpression vector into oral cancer cells and examining the cell growth, along with their migration, invasion, and adhesion abilities after TIMP3 restoration." (PMID 31624299, 2019). "However, whether the abnormal expression and promoter methylation of TIMP3 facilitates oral cancer metastasis remain unclear." (PMID 31624299, 2019). "Furthermore, we examined whether TIMP3 is regulated by the hypermethylation of promoters by analyzing its methylation status in oral tissues and oral cancer cell lines through pyrosequencing." (PMID 31624299, 2019). "To determine the contribution of TIMP3 to oral carcinogenesis, we restored TIMP3 expression in SCC9 and TW2.6 oral cancer cell lines." (PMID 31624299, 2019). "Therefore, we hypothesized that the upregulation of TIMP3 may promote EMT in oral cancer cells." (PMID 31624299, 2019).
oral cancer (continued). "However, it is important to mention here that the relationship between TIMP3 expression and cancer is not as straight as increased TIMP3 plasma levels have been associated with poor prognosis and decreased overall survival in oral cancer and head and neck cancer." (PMID 30988064, 2019). "We determined the promoter methylation levels of p16INK4a, RASSF1A, TIMP3, and PCQAP/MED15 TSGs in salivary DNA from oral cancer (OC) and oropharyngeal cancer (OPC) patients, using methylation-specific PCR coupled with densitometry analysis." (PMID 31013839, 2019). "Results showed that the methylation status of the fragments a, b, and c was lower in the normal oral cell lines than in the oral cancer cell lines, whereas the cell lines SCC9 and TW2.6 with lower TIMP3 mRNA expression were highly methylated in fragments b and c." (PMID 31624299, 2019). "In this study, we observed a significant downregulation of TIMP3 expression in oral cancer tissues compared with adjacent normal tissues, suggesting that the loss of TIMP3 might be a critical event in the pathogenesis of oral cancer." (PMID 31624299, 2019).
osteosarcoma (9 papers, 2015 to 2024). A usually aggressive malignant bone-forming mesenchymal neoplasm, predominantly affecting adolescents and young adults. "Overexpression of miR-222-3p was associated with the downregulation of TIMP3 in osteosarcoma and promoted cells proliferation and invasion." (PMID 35008952, 2022). "In the present case–control study, we investigated the associations between 10 SNPs in TIMP2 and TIMP3 genes and osteosarcoma risk in Zhejiang population." (PMID 33725949, 2021). "The “AT” haplotype in the TIMP3 (consisted of rs9609634 and rs11547635) was associated with decreasing the osteosarcoma risk (OR = 0.64, 95% CI: 0.43–0.91, P = .046)." (PMID 33725949, 2021). "The most frequent haplotype was used as reference, haplotype analysis of genes TIMP2 and TIMP3 detected significant association with the risk of osteosarcoma." (PMID 33725949, 2021). "This study aimed to explore the role of TIMP3 in the cisplatin sensitivity of osteosarcoma and its underlying molecular mechanisms in vitro and in vivo." (PMID 29731768, 2018). "Second, the intermediate molecular mechanisms underlying the link between IL-6 and TIMP3 and the downstream signaling of TIMP3 in osteosarcoma should be better clarified." (PMID 29731768, 2018). "Therefore, we performed a case-control study to analyze the association between the TIMP2 and TIMP3 genes and the risk of osteosarcoma from the teenagers in Zhejiang Province." (PMID 33725949, 2021). "The “Ars9609634Trs11547635” of TIMP3 was associated with reducing the osteosarcoma risk." (PMID 33725949, 2021). "However, few previous studies have reported associations between TIMP3 gene polymorphism and osteosarcoma risk." (PMID 33725949, 2021). "Taken together, TIMP3 expression was negatively associated with osteosarcoma progression." (PMID 29731768, 2018). "This study aimed to explore whether TIMP2/TIMP3 polymorphisms influenced the osteosarcoma risk." (PMID 33725949, 2021). "We aimed to investigate the crosstalk between IL-6 and TIMP3, and to determine whether TIMP3 influences cisplatin sensitivity, proliferation, migration, and invasion of osteosarcoma cells to reveal the mechanisms underlying osteosarcoma drug resistance." (PMID 29731768, 2018). "TIMP3 overexpression improves the sensitivity of osteosarcoma cells to cisplatin by inhibiting AKT activation and IL-6 production." (PMID 38542164, 2024). "The expression of the TIMP2 and TIMP3 genes in osteosarcoma histiocytes was analyzed by immunohistochemistry." (PMID 33725949, 2021). "The expression of TIMP3 was higher in patients with cisplatin-sensitive osteosarcoma than in those with insensitive osteosarcoma." (PMID 29731768, 2018). "The Transwell assay also showed that TIMP3 expression was negatively correlated with osteosarcoma cell migration and invasion." (PMID 29731768, 2018). "Overall, our study revealed that the expression of TIMP3 correlated positively with cisplatin sensitivity in osteosarcoma." (PMID 29731768, 2018). "Our study confirmed the involvement of the IL-6/TIMP3/Caspase pathway in vitro and in vivo, and revealed the important role of TIMP3 in cisplatin sensitivity in osteosarcoma." (PMID 29731768, 2018). "In the present study, we showed that the expression of TIMP3 was positively correlated with cisplatin sensitivity in patients with osteosarcoma." (PMID 29731768, 2018). "We also investigated the effects of the overexpression and knockdown of TIMP3 on proliferation, chemoresistance, migration, and invasion of osteosarcoma cell lines in vitro." (PMID 29731768, 2018). "Our findings show that TIMP3 levels correlated positively with cisplatin sensitivity in osteosarcoma, which is regulated by the IL-6/TIMP3/Caspase pathway in vitro and in vivo." (PMID 29731768, 2018). "The proliferation of osteosarcoma cells was inhibited by TIMP3 overexpression, whereas TIMP3 knockdown had an antagonistic effect." (PMID 29731768, 2018).
osteosarcoma (continued). "We observed that TIMP3 overexpression increased the rate of apoptosis in the osteosarcoma cells treated with cisplatin." (PMID 29731768, 2018). "We compared TIMP3 expression levels between patients with cisplatin-sensitive and -insensitive osteosarcoma." (PMID 29731768, 2018). "We then examined the role of TIMP3 in the resistance of osteosarcoma cells to cisplatin using CCK-8 assays and Saos2-lung cells overexpressing or knocked down for TIMP3." (PMID 29731768, 2018). "Our results implied that TIMP3 overexpression enhanced cisplatin-induced apoptosis in osteosarcoma cells." (PMID 29731768, 2018). "Downregulation of TIMP3 by miR-222-3p increases proliferation and osteosarcoma cell metastasis." (PMID 38542164, 2024). "In addition, we first used IHC to detect the expression of the TIMP2 and TIMP3 gene in normal histiocytes and osteosarcoma histiocytes." (PMID 33725949, 2021). "Our study provides a deeper understanding of chemoresistance to cisplatin in osteosarcoma, and suggests that TIMP3 could potentially aid in the design of new anticancer drugs and the development of new therapeutic methods to treat osteosarcoma." (PMID 29731768, 2018). "Taken together, we concluded that TIMP3 overexpression in osteosarcoma cells may directly or indirectly increase the expression and/or activity of the caspase family proteins, eventually resulting in improved sensitivity to cisplatin." (PMID 29731768, 2018). "By contrast, we speculated that the activation of TIMP3 would have the opposite effect on the expression and/or activity of the caspase family proteins, which would increase the sensitivity of osteosarcomas to cisplatin." (PMID 29731768, 2018). "Interleukin (IL)-6 and TIMP3 play important roles in the drug resistance of osteosarcoma; however, their relationship in this process remains unclear." (PMID 29731768, 2018). "Our previous study showed that TIMP3 could regulate osteosarcoma cell migration, invasion, and chemotherapeutic resistance in vitro." (PMID 29731768, 2018). "This suggested that Akt is a target of TIMP3 in osteosarcoma." (PMID 29731768, 2018). "The TIMP3 pathway could represent a target for new therapies to treat osteosarcoma." (PMID 29731768, 2018). "Thus, TIMP3 could be an effective molecular marker for predicting and even regulating the sensitivity to cisplatin in patients with osteosarcoma." (PMID 29731768, 2018). "Therefore, IL-6 and TIMP3 play important roles in the drug resistance of osteosarcoma." (PMID 29731768, 2018). "Over-expression of miR-181a leads to increased viability of osteosarcoma cells and induced cell proliferation by augmenting BCL2, MMP9; and apoptosis was inhibited by down-regulation of p21 and TIMP3 expression." (PMID 32932883, 2020). "This is probably because high TIMP3 and low CTGF and PPARγ expression indicates a more differentiated and less stem-like osteosarcoma sub-type with high Wnt and Hippo signaling." (PMID 27528232, 2016). "Low TIMP3 (Wnt target), and high CTGF (YAP target) and PPARγ expression suggest a more aggressive osteosarcoma sub-type with low Wnt and Hippo signaling, and a higher propensity to adipocytic differentiation as reflected by high PPARγ expression." (PMID 27528232, 2016). "TIMP3 was constitutively overexpressed because of lentivirus transfection, and siRNA did not produce this effect; therefore a nude-mouse model of primary osteosarcoma was established by injecting Saos2-lung cells with and without TIMP3 overexpression into the bone marrow cavity of mouse tibiae." (PMID 29731768, 2018).
age-related macular degeneration (8 papers, 2007 to 2023). Age-related loss of vision in the central portion of the retina (macula), secondary to retinal degeneration. "Of note, SYN3/TIMP3 was also identified as susceptibility locus for age-related macular degeneration, a late-onset neurodegenerative disease of the retina involving amyloid-β pathology." (PMID 29860282, 2018). "LUM and TIMP3, associated with corneal structure and age-related macular degeneration, respectively, were among visual perception genes influenced by LCPUFA." (PMID 17426818, 2007). "Histologically, DLDs have been demonstrated to react with antibodies against C5, TIMP3, vitronectin, and amyloid P component, which are the markers of age-related macular degeneration (AMD)-associated drusen, thus outlining a similarity between DLD and the typical drusen seen in patients with AMD." (PMID 37371724, 2023). "A better understanding of the structure and function of wild-type and mutant TIMP3 could provide important clues to the pathogenesis of Sorsby Fundus Dystrophy as well as the more common and related age-related macular degeneration." (PMID 36430707, 2022).
emphysema (8 papers, 2004 to 2020). "This was partly answered by an important finding, which showed that individuals carrying the TIMP-3 p.Y191C mutation presented with bronchiectasis and emphysema before developing SFD." (PMID 31877820, 2019). "In this line, TIMP3 should be screened in patients with familial bronchiectasis or emphysema, particularly if a medical history of visual loss or choroidal neovascularization is reported." (PMID 27601084, 2016). "However, recent findings described two SFD families with a history of pulmonary disease, where individuals over 50 years in one family (carrying the TIMP-3 p.Y191C mutation) were diagnosed with severe emphysema." (PMID 31877820, 2019). "An identical mechanical response to normal Vt mechanical ventilation has been observed in a TIMP3 KO murine model of emphysema." (PMID 30662910, 2018). "TIMP-3 null mice develop emphysema while human studies show TIMP-1 and -2 are raised in the airways of COPD subjects and TIMP-2 polymorphisms are associated with CLE." (PMID 27460105, 2016). "Fifteen genes were thus found to be upregulated in fibroblasts of emphysema, among them IGFBP-rP1 (4.9-fold), LOX (3.3-fold), LOXL2 (3.9-fold) and TIMP3 (3.0-fold), whereas 121 genes were downregulated, among them CDK4 (6.3-fold), FOSL1 (4.8-fold), OAZ1 (6.7-fold) and IGFBP-5 (5.3-fold)." (PMID 16504044, 2006). "TIMP-3 plays an important role in lung development since the TIMP-3 null mouse develops a lung phenotype of spontaneous air space enlargement, similar to that of pulmonary emphysema and has decreased bronchiole branching during morphogenesis." (PMID 16390543, 2006).
head and neck cancer (8 papers, 2011 to 2024). A primary or metastatic malignant neoplasm affecting the head and neck. "TIMP3 has been described as a tumour suppressor in several human malignancies, including liver, lung, thyroid, colon, and head and neck cancer." (PMID 38542164, 2024). "Genome–wide analysis of head and neck carcinomas showed that the TIMP3 gene acquires DNA hypermethylation." (PMID 29744893, 2018). "However, some contradictory results imply that TIMP-3 expression is increased in certain types of cancers and that high TIMP-3 expression is linked poor prognosis in head and neck cancer." (PMID 25171061, 2014).